FAM90A14 (family with sequence similarity 90 member A14)
Synonyms: FAM90A14P
Tractability: No criterion of Open Targets' tractability assessment is met for any kind of drug.
Gene: Protein-coding gene on chromosome 8 (7,715,443 to 7,718,453, forward strand). Ensembl gene ENSG00000285814.
Subcellular location (Human Protein Atlas): Nucleoplasm; Nucleoli
Homologues: Orthologues: mouse Fam90a1b (28% identical), mouse Fam90a1a (27% identical), rat Fam90a1l1 (26% identical). Paralogues in human: FAM90A15 (99% identical), FAM90A13 (99% identical), FAM90A5 (99% identical), FAM90A23 (99% identical), FAM90A24 (98% identical), FAM90A3 (98% identical), FAM90A11 (98% identical), FAM90A16 (98% identical), FAM90A17 (98% identical), FAM90A9 (98% identical), FAM90A12 (98% identical), FAM90A18 (97% identical), and 9 more.